CCL2 (C-C motif chemokine ligand 2)
Diseases named in the same sentence as CCL2 in open-access papers (continued):
Sharing a sentence is not in itself a finding about the gene and the disease.
tumor (continued). "TAMs that originate from circulating monocytes are recruited to the hypoxic tumor area by tumor-derived factors, such as colony-stimulating factor-1 (CSF-1), VEGF-A, and chemokine (C–C motif) ligand 2 (CCL2)." (PMID 33230600, 2021). "Accordingly, higher expression of CCL2 and CSF1 were observed in tumor samples of CREBBPmut patients than those of CREBBPwt patients by RNA sequencing." (PMID 33431788, 2021). "In support of our hypothesis, recent findings link CCL2 to the inflammation and cancer pathogenesis and provide evidence that CCL2 production in tumors is due to complex interactions between tumor and non-tumor cells, both cells contributing to the high tumor-associated CCL2 levels." (PMID 34639088, 2021). "CCL2 (MCP1), which interacts with CCR2, is an alternative mechanism that influences macrophage-related myeloid recruitment to tumors and subsequent tumor progression." (PMID 33953710, 2021). "CCL2 KD, and consequently reduction in TAM densities, led to a striking reduction of tumor cell proliferation and a concomitant increase in tumor necrosis." (PMID 34824220, 2021). "Overexpressing chemokines, such as CCL2 (MCP-1) and CCL3, accompanying the recruitment of macrophages, is a common phenomenon in human tumours." (PMID 33808304, 2021). "Irradiation promotes IL-6 production by the tumor microenvironment, which results in STAT3 phosphorylation and subsequent anti-inflammatory CCL2, CCL4, VEGF, and TGF-β cytokine production." (PMID 33800829, 2021). "Blockade of the CCL2/CCR2 axis was also shown to inhibit the recruitment of TAMs leading to enhanced infiltration of CD8+ T cells and improved anti-tumor immunity." (PMID 33815418, 2021). "The chemokine (C-C motif) ligand 2 (CCL2)/chemokine (C-C motif) receptor 2 (CCR2) axis drives chemoresistance and immunosuppressive mechanisms in the tumor microenvironment." (PMID 34358103, 2021). "In these systems, depletion of colon macrophages or blockage of macrophage migration in response to C-C motif chemokine ligand 2 (CCL2) effectively inhibits microbiota-driven intestinal inflammation and reduces or abolishes tumor formation." (PMID 33969420, 2021). "It was well documented that certain chemokines such as CCL2 and CSF-1 or CXCR2 ligands promoted the recruitment of MDSCs from the circulation to the tumor microenvironment." (PMID 33791296, 2021). "CCL2 (also named MCP-1), which is released by tumor cells, is a chemotactic factor that recruits CCL2R+ monocytes, T cells and NK cells." (PMID 34368156, 2021). "In the context of cancer, we highlight here the complex and sometimes underappreciated roles of the CCL2/CCR2 axis in regulating abundance and functions of monocytes/MØs, T cells (particularly Tregs) and tumor cells." (PMID 34804061, 2021). "Six1 overexpression in MC38 recruits TAMs by increasing the expression of macrophage-specific colony stimulating factors CCL2 and CCL5, further promoting the growth and metastasis of CRC and remodeling the tumor matrix." (PMID 34445193, 2021). "EVs derived from NB cell lines have been demonstrated to affect BM-MSCs: they stimulated the secretion of tumor-supportive cytokines and chemokines from BM-MSCs in vitro, most notably IL-6, IL-8/CXCL8, vascular endothelial growth factor (VEGF), and CCL2/MCP-1." (PMID 33287630, 2021). "Inhibition of CCL2/CCR2 or CSF1/CSF1R signaling pathway can reduce the intratumoral infiltration of M2-TAM and inhibit tumor growth and metastasis." (PMID 34583750, 2021). "Chemoattractants such as CCL2 (or MCP1), secreted by cancer cells, can stimulate microglia via CCR2 activation, and recruit the microglia to the tumor microenvironment to support invasiveness through IL-6 expression." (PMID 34566949, 2021). "MDSC differentiation is facilitated by the tumor-derived cytokines, including G-CSF, GM-CSF, VEGF, and chemokines such as CCL2 and CXCL12." (PMID 33129234, 2021).
tumor (continued). "As expected, treatment with either antibody markedly decreased the expression and secretion of CCL2 and CCL5 in these tumor cells, with the most significant decrease in the combination treatment group." (PMID 33537094, 2021). "After CCL2 administration, intratumoral MMP9 expression was increased significantly and the survival time was declined dramatically in tumour‐bearing mice." (PMID 34464477, 2021). "It is possible that soluble factors, including CCL2, SDF-1α, M-CSF, GM-CSF, and G-CSF, are secreted by tumour cells." (PMID 33452462, 2021). "For example, the blockade of CSF1/CSF1R pathway and CCL2/CCR2 axis prevented TAM recruitment and improved anti-tumor immunity." (PMID 34575463, 2021). "Our results demonstrated that there was a close relationship between CCL2 and M‐MDSCs in PDAC tissues, which promoted tumor progression." (PMID 34525267, 2021). "It has been reported that CCL1, CCL2 and CCL21 affect tumor metastasis and progression through direct or indirect interactions with lymph nodes." (PMID 34321012, 2021). "CCL3 secretion by TAMs was found to be induced by CCL2/CCR2 and IL-33, with these TAMs reported to mediate metastatic spread in different tumor models." (PMID 34988021, 2021). "Because MDSCs are recruited to the TME by tumor cells, blocking their migration using a CCR5 antagonist and CCL2 inhibitors seems to be a promising therapeutic approach." (PMID 34025641, 2021). "Our previous reports demonstrated that IL-6, CCL2, and PAI-1 derived from CAF-like cells also have tumor-promoting roles, including the induction of migration and invasiveness of ESCC cell lines." (PMID 34572779, 2021). "CSCs also produce various chemokines, such as CCL2 (MCP1), to recruit immunosuppressive CCR2+ cells, including Tregs and MDSCs, and CXCL1/2 to recruit CXCR2+ MDSCs that enhance tumor survival." (PMID 33535613, 2021). "iCAFs secrete inflammatory factors such as interleukin (IL)-6, IL-8, CCL2, and CXCL2 that promote tumor growth and also promote T-cell dysregulation by promoting expression of immune checkpoint inhibitors (PD-1, TIM-3)." (PMID 34957115, 2021). "One key chemokine utilized by tumor cells is C–C motif chemokine ligand 2 (CCL2), which functions to enhance angiogenesis and attract macrophages and microglia to the TME, further contributing to tumor growth." (PMID 34571905, 2021). "Other types of miRNAs include the tumor suppressors comprising of miR-126, whose main function is to suppress MSC recruitment in the TME by inhibiting SDF-1 and CCL2." (PMID 34122412, 2021). "To further determine the specific expression of tumor-derived and host-derived CCL2, we isolated CD45− cells, CD45+ immune cells, CD11b+ F4/80+Ly6G− TAMs, and CD11b+ F480- Ly6G+ Ly6C-/low G-MDSCs from the tumor tissue of Hepa1-6 tumor-bearing mice." (PMID 34593796, 2021). "Our study indicates that PDAC cells produced CCL2, which promoted localized M‐MDSC recruitment and immune suppression, thereby promoting tumor progression." (PMID 34525267, 2021). "Here we found eustress overcame the PD-1 resistance via SNS/β-ARs signaling and increased the tumor-specific CD8+ T cell infiltration and reaction via silencing CCL2." (PMID 34593796, 2021). "It has been reported that CCL2 contributed to the establishment of the PMN and the homing of tumour cells." (PMID 34464477, 2021). "In several solid tumors, macrophages are recruited to the tumor site through a gradient of chemotactic molecules, such as CCL2 (also known as MCP-1), colony stimulating factor 1 (CSF-1, also known as M-CSF) or several CXCL chemokines." (PMID 34572939, 2021). "Some chemokines, such as CCL2, CCL5, and CXCL8/IL-8, attract leukocytes and macrophages to the tumor site, where they can release vascular endothelial growth factor (VEGF) and other angiogenic factors that help new blood vessels form." (PMID 34943797, 2021).
tumor (continued). "CoREST1 on coordination with LSD1 promotes expression of VEGF-A and proinflammatory factors CCL2/MCP-I and CXCL16 and contributes to angiogenesis and tumor inflammatory responses in breast cancer." (PMID 34901003, 2021). "In parallel with the results of inhibited tumour growth and increased production of MCP-1/CCL2 we have observed the increased number of early interstitial pneumonias in mice injected with HT29-Snail cells, as compared to HT29-pcDNA cells (group IV and II)." (PMID 33419021, 2021). "S100A14 overexpressed in breast cancer cells promotes metastasis by activating the RAGE-NFκB signaling pathway resulting in the upregulation of CCL2 and CXCL5 expression in the tumor cells." (PMID 34572138, 2021). "HDAC5 inhibits suppressor of cytokine signaling 3 (SOCS3), which leads to an increase of C-C motif chemokine ligand 2 (CCL2), recruits CCR2+ macrophages, promotes macrophages to reaggregate into tumor microenvironments, and promotes tumor recurrence." (PMID 34880761, 2021). "Knockdown or antibody neutralization of CCL2 in breast xenograft models inhibits infiltration of CCR2+ macrophages and reduces tumor growth and metastasis." (PMID 33888841, 2021). "Here, treatment with anti-CCL2 mAb reduced TAM accumulation, consequently reducing angiogenesis and tumor growth." (PMID 34638388, 2021). "To further determine the role of CCL2/CCR2 signaling on EE-mediated antitumor immunity, we investigated tumor-infiltrated immune cells in DEN/CCl4-induced tumor by flow cytometry analysis." (PMID 34593796, 2021). "In MM, it has been reported that both tumor cells and BM mesenchymal stromal cells produce chemokines such as CXCL12, CCL2, CCL3, and CCL14 that promote macrophage migration to the tumor niche and polarize macrophages towards an M2-like phenotype in vitro." (PMID 33435306, 2021). "We analyzed the expression of CCL2, β1-AR, β2-AR, β3-AR, and CD45 using in situ immunostaining in DEN + CCl4-induced tumor tissue." (PMID 34593796, 2021). "However, CCL2 has also been reported to be a critical mediator of optimal anti-metastatic entrainment of G-CSF-stimulated neutrophils, and this type of tumour-entrained neutrophils inhibits tumour cell seeding at a distant pre-metastatic site by generating H2O2." (PMID 35006432, 2021). "Angiopoietin-2 can be secreted by tumor ECs, which leads to an autocrine activation of STAT3 signaling with secretion of CCL2 and higher expression of ICAM1." (PMID 34073394, 2021). "Targeting the CCL2/CCR2 pathway, responsible for the recruitment of these immunosuppressive myeloid cells, enhanced anti-tumor immunity in the residual tumor, and thereby overcame the resistance to anti-PD-1 therapy." (PMID 33936033, 2021). "Conversely, neutralizing anti-CCL2 antibody or knockdown of CCL2 remarkably blocked the migration of MDSCs and abrogated FAP(+) CAF-mediated tumor promotion." (PMID 33292459, 2020). "The immune cell recruitment involves several inflammatory mediators, such as CCL2, S100A8/9, IL-1β, IL-5, GM-CSF and lipid-derived PGE2, which promote cancer-related inflammation, emergency myelopoiesis and tumor progression." (PMID 32823961, 2020). "We treated GBM cells and PBMCs with IL-1β and found dramatically increased expression levels of the proinflammatory and tumor-promoting mediators COX2, IL-1β, CCL2, and IL-8 in both GBM cells and PBMCs." (PMID 32069807, 2020). "Macrophages, which in lean people show an M2 anti-inflammatory phenotype, during obesity are switched to an M1 pro-inflammatory profile, expressing tumor-promoting cytokines, such as TNF, IL-6, IL-1β and chemokines, such as CCL2 and MIF." (PMID 32650452, 2020). "Proinflammatory pathways are upregulated in KRAS-dependent tumors, including increased production of the chemokines IL-1β, CCL7, and CCL2, as a result of crosstalk between KRAS-mutant tumor cells and host myeloid cells." (PMID 33335263, 2020).
tumor (continued). "Snail expressed tumor cells not only recruited macrophages by secreting cytokines such as CCL2, CCL5, and IL-6, but also secretes tumor-derived exosomes (TEXs) which contains miR-21 to induce M2-type polarization of macrophages." (PMID 33224886, 2020). "The cells of tumor and TME secrete CCL2 and macrophage colony-stimulating factor (M-CSF) and attract a large number of inflammatory monocytes to tumor sites where they differentiate into TAMs due to secretion of IL4, IL10, and IL13." (PMID 32582698, 2020). "Antibodies against CCL2/CCR2 and CCL5 have been employed in preclinical models in combination with checkpoint blockade immunotherapy with encouraging results in several tumor types." (PMID 32580431, 2020). "TAMs are recruited into the tumor by chemoattractants, such as colony-stimulating factors 1 (CSF1) and monocyte chemoattractant protein 1 (MCP-1/CCL2)." (PMID 32283687, 2020). "Together, they elicit a cytokinome, that includes CCL2 and IL13, enabling crosstalk between cancer cells and host macrophages that drives tumor progression." (PMID 31933479, 2020). "Monocyte-chemoattractant protein 1 (CCL2), VEGFα, and PDGFαβ are well known to be highly expressed in tumor microenvironment and attract MSCs to the site of tumor." (PMID 32793565, 2020). "The modulation of the tumour environment also has a strong rationale, such as targeting the TGF‐β pathway or chemo‐attractive axes such as that of CCL2/CCR2." (PMID 32112478, 2020). "Several murine and human studies have proven that the depletion of CSF-1, CCL-2, VEGF and EGFR lowered the TAMs infiltration, and, implicitly, tumor progression and metastasis." (PMID 33228048, 2020). "MDSCs are mobilized from the bone marrow and recruited into the primary tumor site through various chemo-attractant factors such as M-CSF, GM-CSF, CCL-2 (MCP-1), CCL-5 (RANTES), Bv8, which are particularly secreted in hypoxic regions of the tumor." (PMID 32580431, 2020). "To further explore the function of tumor infiltrating macrophages in esophageal carcinogenesis, we constructed ESCC mouse model with CCL2 and CCR2 gene deletion." (PMID 32103760, 2020). "As for humoral factors, VEGF, macrophage migration inhibitory factor (MIF), IL-6, IL-4/13, IL-10, TGFβ, POSTN, colony-stimulating factor-1 (CSF-1), CCL2, CXCL12, and COX-2/PGE2 directly or indirectly regulate the immunosuppressive tumor microenvironment." (PMID 32707672, 2020). "CCL2, which has been reported in breast cancer, gastric cancer, ovarian cancer, and CRC, is the most representative chemokine that induces MDSC in tumor tissue." (PMID 32707869, 2020). "The therapies using various antibodies or kinase inhibitors inhibit the CCL2/CCR2-, CXCL12/CXCR4-t, or CSF-1/CSF-1R-dependent monocyte/macrophage recruitment into the tumor." (PMID 33352942, 2020). "We therefore examined secretome profiles of tumour-conditioned (BLM-CM and OMC-CM) and control media (Fb-CM and OSC-CM), and focused our attention on CCL-2, IL-6 and PGE2, factors known to play a role in tumour modulation of myeloid functions." (PMID 32488012, 2020). "AR in CAFs activates a signaling network which suppresses the expression of inflammatory cytokines, such as CCL2 and CXCL8, which have tumor-promoting properties." (PMID 32668821, 2020). "For example, preclinical studies showed that targeting CCL2 or the CCL2 receptor (CCR2) on tumor infiltrating macrophages improved chemotherapeutic efficacy, inhibited metastasis and increased anti-tumor T-cell responses." (PMID 33059744, 2020). "The neoplastic stromal cells are of osteoblastic origin and secrete high levels of chemokines (e.g. MCP-1 (CCL2) and SDF-1 (CXCL12)) to attract the mononuclear osteoclast precursor cells to the tumour site." (PMID 31728625, 2020). "This accumulation was associated with elevated concentrations of inflammatory mediators (CCL2, CCL3, CCL4, CCL5, IL-8, and CXCL10) involved in MDSC migration to and activation in the tumor microenvironment." (PMID 32005273, 2020).
tumor (continued). "Both CAMs and AAMs are derived from monocytes, which infiltrate wound beds or tumor microenvironments in response to secretion of chemokine ligand 2 (CCL2, also known as MCP-1)." (PMID 33069212, 2020). "Cancer cells often express increased levels of the chemokine CCL2; also known as monocyte chemoattractant protein 1, MCP1), which recruits MDSCs (expressing the CCR2) in the site of tumor inflammation." (PMID 32656079, 2020). "On the other hand, with the multifunctional activities of chemokines, expression of CCL2 had a positive role in TME and anti-tumor immune response." (PMID 32483450, 2020). "The CCL2 and CCR2 signaling pathway mediates peripheral monocyte trafficking into the tumor microenvironment." (PMID 32780724, 2020). "Immunohistochemically, the expression of CCL2+ cells and CXCL10+ cells in tumor and peri-tumor were higher than in normal brain tissues, and celecoxib decreased the number of these cells." (PMID 32943658, 2020). "To further validate the impact of CCL2 on CTLs depletion, we detected the distribution of CCL2 and CD8 in tumor tissues with ESCC patients (cohort II)." (PMID 32103760, 2020). "The tumour‐derived chemokines and cytokines, such as CCL2, M‐CSF, VEGF and TGF‐β often recruit TAMs to the tumour microenvironment." (PMID 32910558, 2020). "The chemokine C-C motif ligand 2 (CCL-2) is a chemoattractant protein for monocytes, which are secreted at high levels by cancer cells to recruit macrophages to infiltrate the tumor." (PMID 32545155, 2020). "Accumulation of CCL2-mediated macrophages were negatively connected with CD8+ T cells amount and promoted tumor progress." (PMID 32483450, 2020). "The expression of chemokines for CCR2 (Ccl2 and Ccl7) or CCR5 (Ccl3, Ccl4, and Ccl5) in tumor-bearing lungs, chemoattractants for monocytes/macrophages, was unchanged in FROUNT-cKO mice." (PMID 32001710, 2020). "The tumor cell lines, NA13, B16F10 and E0771, express CCL2 and PD-L1 in vitro and PD-L1 in vivo to varying levels." (PMID 33247183, 2020). "Circulating monocytes are recruited by several tumor-derived chemo-attractants as CCL2 (MCP-1), CCL3 (MIP-1), CXCL12 (SDF-1), and CSF-1 at tumor sites where they differentiate into TAMs and facilitate tumor progression." (PMID 33374253, 2020). "Reduction in PTEN expression increased the secretion of C-C motif chemokine ligand 2 (CCL2), resulting in ionized calcium-binding adapter molecule 1 (IBA1) expressing myeloid cell infiltration in the BrM tumor." (PMID 32906592, 2020). "In TRAMP mice with metastatic prostate adenocarcinoma expressing high levels of CCL2, the expression of CCR2 in SV40 Tag-specific CD8 lymphocytes increased T cell homing to the tumor." (PMID 33013822, 2020). "Systemic administration of CCL2 monoclonal antibody, carlumab (CNTO 888), in VCaP xenograft model mice attenuated TAM infiltration and retarded tumor growth." (PMID 32824865, 2020). "In various cancers, the crosstalk of TAMs with tumor cells via the CCL2/CCR2 axis play multiple roles in cancer development, such as monocyte/macrophage recruitment at the tumor site, tumor progression, EMT, invasion, and metastasis." (PMID 32219066, 2020). "Recruitment of these cells to the tumor microenvironment is mediated by different cytokines, including VEGF, chemokine C-C motif ligand 2 (CCL2), and macrophage colony stimulating factor (MCSF)." (PMID 32175278, 2020). "TAMs can promote CRC migration, invasion, and circulating tumor cell (CTC)-mediated metastasis via the JAK2/STAT3/miR-506-3p/FoxQ1 axis, enhancing macrophage recruitment through the production of CCL2 by tumor cells." (PMID 32943996, 2020). "CCL2 is also a chemoattractant for MDSCs, which triggers MDSC-dependent suppression of immunological control over the tumor, stimulates macrophage-mediated angiogenic switch and the promotion of tumor growth by these cells." (PMID 32456359, 2020).